IL1A (interleukin 1 alpha)
Diseases named in the same sentence as IL1A in open-access papers (continued):
Sharing a sentence is not in itself a finding about the gene and the disease.
delirium (6 papers, 2022 to 2025). A disorder characterized by confusion; inattentiveness; disorientation; illusions; hallucinations; agitation; and in some instances autonomic nervous system overactivity. "We identified several soluble factors and immune cell types linked to delirium, including IL-1α, IL-22, IL-21, CCL11, CXCL1, CXCL13, and VEGF-A, as well as exhausted B cells and activated T cells." (PMID 41219650, 2025). "The pro-inflammatory cytokines, IL-6, TNF-α, IL-1α, IL-1β, have been implicated in delirium-like behavioral changes, such as impaired concentration, diminished motivation, and psychomotor retardation in critically ill patients." (PMID 36030220, 2022). "In patients with delirium, it was demonstrated that pro-inflammatory cytokines, such as IL-6, IL-1α, IL-1β, and TNF-α, are associated with delirium-like behavioral disturbances, such as diminished concentration, altered motivation, and decreased psychomotor activities." (PMID 41156174, 2025). "Overall, delirium was correlated with several cytokines (decreased IL-22, IL-21, IL-1α), chemokines (increased CXCL1, CCL11, CXCL13), and growth factors (increased HGF, and a tendency towards increased VEGF-A)." (PMID 41219650, 2025). "This study evaluated the effect of nine genetically predicted inflammatory factors (TNF-α, CPR, IL-1α, IL-1β, IL-2, IL-6, sIL-6Rα, Soluble gp130, and IL-8) on delirium." (PMID 37649721, 2023). "There is an increased systemic production of interleukin-1 α (IL-1α), IL-1β, IL-6, IL-10, and tumor necrosis factor α (TNF-α), which are implicated in the pathogenesis of delirium." (PMID 36030220, 2022). "Furthermore, several studies have examined the potential role of IL-1α, IL-1β, IL-2, and IL-8 in the development of delirium." (PMID 37649721, 2023). "The results of this MR analysis did not support that peripheral TNF-α, CRP, IL-1α, IL-1β, IL-2, IL-6, sIL-6Rα, soluble gp130, and IL-8 were causally associated with delirium." (PMID 37649721, 2023). "Whereas, i.c.v. administration of IL‐1α, TNF‐α, and C1q can increase their immunoactivity and mimic delirium‐like behavior in the young mice, and intraperitoneal injection of Ex‐4 attenuated such changes." (PMID 38155547, 2024). "In summary, the MR analysis indicated that there may not be a causal association between delirium and the following factors: TNF-α, CRP, IL-1α, IL-1β, IL-2, IL-6, sIL-6Rα, soluble gp130, and IL-8." (PMID 37649721, 2023).
dementia (6 papers, 2018 to 2024). Loss of intellectual abilities interfering with an individual's social and occupational functions. "Of the estimated genotypic pools, individuals with homozygous alleles for the IL-1α (rs1800587), IL-6 (rs1800796), TNFα (rs361525), and IFNγ (rs2069705) genes were identified in the high-risk group for dementia." (PMID 36389080, 2022). "The relationship between the IL1A-889 C/T polymorphism, with dementia, has been tested in different ethnic groups from different regions, and the results vary." (PMID 36389080, 2022). "We found that IL-1a rs1800587 is associated with the susceptibility to developing dementia (OR = 1.55, 95%; CI = 1.20–2.00; p = 0.001)." (PMID 36389080, 2022). "Our study identifies the allele of IL1-α rs1800587 associated with the risk of dementia, which can facilitate the neuroinflammatory processes in the pathology." (PMID 36389080, 2022). "IL1α is closely associated with the early innate immune response, and raised serum levels in HC participants over years have been associated with increased risk of incident dementia." (PMID 39161876, 2024). "We investigate the combinatorial effect of four (IL-1α, IL-6, TNFα, and IFN-γ) genetic polymorphisms involved in the inflammatory processes of microglial cells in the brain on the susceptibility to dementia in Mexican individuals." (PMID 36389080, 2022). "In Mexico, less has been explored about the relationship of the genes’ pro-inflammatory cytokines released from activated microglia (IL-1α, IL-6, TNFα, and IFNγ) with dementia." (PMID 36389080, 2022). "Incident dementia was associated with increases in all five serum cytokines during the follow-up, and the strength of the significance remained for TNF-α, IL1-α, and IL-1β after applying the Bonferroni correction." (PMID 30510525, 2018). "In clinical and pre-clinical models of dementia and AD, neuroinflammatory mediators such as the COX enzyme and pro-inflammatory cytokines, including TNF-α, IL-6, IL-1α, and IL-1β, trigger the nervous system’s inflammatory responses." (PMID 36840284, 2023). "The involvement of cytokines in dementia is supported by studies showing that the levels of pro-inflammatory cytokines [e.g., tumor necrosis factor alpha (TNF-α), interleukin (IL)-1α, IL-1β, IL-6, and IL-8] are altered." (PMID 30510525, 2018). "The cytokines IL-13 and IL-1α were significantly associated with less tau pathology in APOE ε4 negative participants and were not independently predictive of dementia." (PMID 32076055, 2020).
dengue (6 papers, 2014 to 2025). "In dengue, IL-1A release by infected macrophages contributes both to endothelial activation and to vascular leakage." (PMID 40927453, 2025). "For instance, CIITA continues to be important by providing resistance factors to modern infectious diseases such as Ebola virus and SARS-CoV-2, and IL18R1 has been shown to confer protection against more severe clinical dengue phenotypes through IL1α downregulation." (PMID 36726304, 2023). "We also observed down regulation of IL1α, which may point to the possible role of TNFα and IL1α in dengue pathogenesis." (PMID 24727912, 2014). "Inflammation mediators including IL-1α, IFN-γ, IL-10, IL-8, IP-10, MCP-1 and sVCAM-1 displayed significant differences on day 8-10 of illness between mild and severe dengue patients." (PMID 27301555, 2016). "By using multiplex immunoassay, we compared host cytokine profiles between acute CHIKV and DENV infections by analysing serum cytokine levels of IL-1α, IL-4, IL-5, IL-8, IL-13, RANTES, MCP-3, eotaxin, PDGF-AB/BB, and FGF-2 from the sera of acute chikungunya and dengue fever patients." (PMID 34215212, 2021). "A paired comparison of these 15 cytokines (irrespective of the treatment group) showed that 12 (eotaxin, FGF-2, IFN-γ, IL-10, IL-1Ra, IL-1α, IL-8, IP-10, MCP-1, MDC, TNF-α and sCD40L) were differentially expressed between baseline and acute phase of dengue illness." (PMID 27459266, 2016). "Moreover, higher level of TNF-α (P =0.004) on day 6–7 and higher levels of IL-1α (P = 0.012) and IFN-γ (P = 0.001) on day 8–10 of illness were observed in severe dengue patients than mild ones." (PMID 27301555, 2016). "However, Level of IL-1α in dengue patients has not been reported." (PMID 27301555, 2016).
esophageal cancer (6 papers, 2019 to 2024). A primary or metastatic malignant neoplasm involving the esophagus. "On the other hand, the anti-cancer activity of IL-1RA has been reported, with a previous study showing that IL-1RA suppresses esophageal cancer cell growth through inhibition of IL-1α-VEGF signaling." (PMID 37461111, 2023). "In contrast to IL-1α and IL-1β which promotes inflammation, IL-1RA has been demonstrated to suppress angiogenesis accompanying gastric and esophageal cancer cell growth." (PMID 32408627, 2020). "In esophageal cancer cells or cancer stem cells, metformin reversed the expression of several inflammatory genes, including IL-8, Lin28B, Let-7, IL-1α, IL-1β, IL-1, and vascular endothelial growth factor (VEGF), preventing cellular proliferation and transformation." (PMID 30765814, 2019). "IL-1ra could also suppress the growth of esophageal cancer cells by blocking IL-1α." (PMID 35928634, 2022).
gingivitis (6 papers, 2014 to 2025). A disorder involving inflammation of the gums; may affect surrounding and supporting structures of the teeth. "Prevotella was associated with clinical signs of gingivitis and with an increase in the levels of inflammatory mediators such as IL-1α, IL-1ß, IL-1Ra, and lactoferrin in GCF." (PMID 39527605, 2024). "Clinical data showed that changes in IL-1α represent a transient and reversible mediator response that co-varies with changes in clinical signs during the induction and resolution of gingivitis." (PMID 36305963, 2023). "IL-1α was found to be higher in the crevicular fluid of patients who had been subject to experimental gingivitis." (PMID 24790719, 2014). "In fact, during the development of gingivitis, there are consistent modifications in IL-1α, IL-1β, IL-8, MCP-1, and MIP-1β levels, which may vary according to phenotype and GCF flow." (PMID 36305963, 2023). "Numerous studies have reported raised levels of immune mediators in experimental gingivitis for GCF, including transforming growth factor beta (TGFβ) and IL-1α." (PMID 35627876, 2022). "Conversely, Bifidobacterium animalis supplementation at a dose of 1 × 109 CFU/day for 2 months significantly reduced bleeding observed during probing, gingival inflammation, and levels of pro-inflammatory cytokines such as IL-1α and MCP-1 in adults with gingivitis." (PMID 41323139, 2025).
Hepatic steatosis (6 papers, 2014 to 2026). Steatosis is a term used to denote lipid accumulation within hepatocytes. "For instance, IL-1α and -1β promote fatty liver disease processes, including liver steatosis, hepatic damage, liver fibrosis, and the recruitment of immune cells induced by inflammation through IL-1 receptor signaling." (PMID 36899958, 2023). "Even though clodronate-mediated KC depletion improves hepatic steatosis in both models, we only observe a decrease in IL-1α expression in clodronate-treated DIO mouse livers compared with control mice." (PMID 25216251, 2014). "In contrast, hepatic steatosis did not correlate with the microbiota but was strongly associated with a gene expression profile primarily characterized by increased expression of the pro-fibrotic Th2 cytokine ll-5 and the pro-inflammatory Il-1α." (PMID 35141703, 2021).
juvenile idiopathic arthritis (6 papers, 2008 to 2023). Juvenile idiopathic arthritis (JIA) is the term used to describe a group of inflammatory articular disorders of unknown cause that begin before the age of 16 and last over 6 weeks. "In line with our results, a previous study found that −889 T IL1A allele, related with higher IL-1α production, was associated with the development of chronic iridocyclitis in juvenile rheumatoid arthritis patients." (PMID 18941541, 2008).
leukemia (6 papers, 2015 to 2024). A malignant (clonal) hematologic disorder, involving hematopoietic stem cells and characterized by the presence of primitive or atypical myeloid or lymphoid cells in the bone marrow and the blood. "Such Benzene network functions are associated with leukemia mechanisms, and several of these functions and processes are mediated by IL1A and PTGS2, which play a central role in the characterization of gene expression associated with benzene exposure." (PMID 37298367, 2023). "While the effect of the secreted IL-1α could be blocked by this treatment, our results suggested that the nuclear IL-1α propiece generated during the process of IL-1α secretion could still promote leukemia growth." (PMID 28152513, 2017). "Monoclonal antibody to IL-1α is being tested in cancer, especially leukemia treatment." (PMID 28152513, 2017). "IL-1a induces MSC production of IL-1a, leukemia-inhibiting factor, G-CSF, and GM-CSF." (PMID 25722881, 2015). "Therefore, inhibition of the enzymatic process of IL-1α cleavage may be a more effective strategy treating cancer and leukemia in the future." (PMID 28152513, 2017). "The mice received p388 cells expressing IL-1α propiece had significantly higher percentages of YFP positive cells in the peripheral blood, demonstrating a higher load of leukemia cells." (PMID 28152513, 2017). "Leukemia BM decreased CXCL12 expression and up-regulated G-CSF, IL-1α, MIP-1β, and MIP-2, compared to normal BMSCs." (PMID 26716419, 2016). "As-A is shown herein to bind to HDC and exhibit a similar effect on leukemia development resulting in inhibition of several anti-inflammatory genes including TNF, IL1A/B, TNFA1P3, and CXCR2, but not IL6." (PMID 39769192, 2024).
myositis (6 papers, 2013 to 2025). "In a retrospective series, IL-1α was significantly elevated in patients who developed ICI-induced myositis." (PMID 36900420, 2023). "Increased IL-1α, IL-21, LIF, and PlGF-1 levels were significantly associated with the incidence of myositis, and the serum levels of six cytokines (BTLA, GM-CSF, IL-4, PD-1, PD-L1 and TIM-3) were higher in patients who developed a rash." (PMID 36159840, 2022). "Increased IL-1α, IL-21, LIF, and PIGF-1 levels were significantly associated with myositis incidence, while the serum levels of six cytokines (BTLA, GM-CSF, IL-4, PD-1, PD-L1 and TIM-3) were higher in patients with rash." (PMID 36159840, 2022). "IL-1α was predominantly expressed in capillary endothelial cells of PM, DM and sIBM muscle biopsies suggesting a prominent role for endothelial cells in myositis pathology." (PMID 23758833, 2013). "The most predominantly reported cytokines in myositis include pro-inflammatory cytokines such as IL-1α, IL-1β, TNF-α and transforming growth factor (TGF)-β." (PMID 23758833, 2013). "In addition, testing of two commonly found autoantibody targets, IL-1α and Jo-1, that have been observed in both healthy persons and patients with myositis, respectively, revealed low level autoantibodies in IVIG just above the cut-off value derived from control children (data not shown)." (PMID 35360001, 2022). "Cultured human myoblasts from patients with myositis constitutively produce a low level of cytoplasmic and secreted IL-15, which was also observed in healthy controls; however, mRNA and protein production was increased in DM patients by stimulation with IL-1α, IL-1β, TNF-α, or IFN-γ." (PMID 30766892, 2019).
nasal polyps (6 papers, 2013 to 2023). "In fact, IL1A with rs17561 allele T has been suggested to be associated with immunopathogenesis of several diseases, including nasal polyposis, chronic rhinosinusitis." (PMID 23927441, 2013). "IL-1α, IL-4, IL-6, IL-8, IL-10, IL-12 (p < 0.001), and Ki-67 (p = 0.001) were decreased in the epithelium of the nasal polyp samples in comparison to the control samples." (PMID 36285981, 2022). "IL-1α, IL-6, IL-8, IL-10, IL-12 (p < 0.001), and IL-4 (p = 0.038) were increased in the subepithelial connective tissue of the nasal polyp samples when compared to the control samples." (PMID 36285981, 2022). "Immunohistochemistry data revealed that IL-1α showed moderate to numerous positive structures in epithelium of control samples, but nasal polyp samples only had few to moderate positive epitheliocytes." (PMID 34208325, 2021). "The amount of IL-1α positive structures in nasal polyps was significantly decreased in epithelium (p = 0.001) and increased in connective tissue (p < 0.001) in comparison to control samples." (PMID 34208325, 2021). "When comparing nasal polyp samples with normal mucosa from control patients, it was apparent that IL-1α, IL-4, IL-6, IL-7, IL-8, IL-10, IL-12 positive structures were significantly decreased in epithelium of the polyps." (PMID 34208325, 2021). "When observing connective tissue, in contrast to epithelium, control samples showed occasional number of IL-1α positive structures and nasal polyp samples had moderate amount of positive cells." (PMID 34208325, 2021). "IL-1α is designated as a key alarmin and therefore is worth examining in the context of CRS to evaluate tissue damage in nasal polyps." (PMID 34208325, 2021). "Besides IL-6, epithelial IL-1α had strong correlations with various factors without a distinctive pattern, and it could be presumed that it functions as an alarmin and has no specific role in inflammation that advances the formation of nasal polyps." (PMID 36285981, 2022).
pulpitis (6 papers, 2019 to 2023). Inflammation of the dental pulp. "Levels of IL-1α analysed with multiplex assay illustrated a significant increase in both reversible (p < 0.01) and irreversible (p < 0.001) pulpitis groups compared to controls." (PMID 34299403, 2021). "IL-1α is increased in the dentinal fluid of irreversible pulpitis compared to normal pulp, however, there is not significant difference compared to reversible pulpitis." (PMID 38947881, 2021). "Dental pulps with pulpitis suffer higher expressions of proinflammatory cytokines (IL-1α, IL-1β, IL-6, and TNF-α) and innate immune response (TLR2, TLR4) than pulps without pulpitis." (PMID 31695620, 2019).
rosacea (6 papers, 2011 to 2025). A chronic erythematous skin disorder that affects the face. "Research indicates elevated levels of proinflammatory cytokines such as IL-1a, along with reduced levels of anti-inflammatory cytokines such as IL-10 in the tears of rosacea patients with ocular symptoms." (PMID 39859986, 2025). "TNF-α, IL-6, IL-1α, and IL-1β are well-characterized inflammatory mediators in rosacea pathogenesis, driving key pathological processes including inflammatory cell infiltration, vascular hyperreactivity, and neuroimmune disorder." (PMID 40378103, 2025). "Specifically, the expression of two NF-κB target genes, namely IL-1α and IL-1β, was elevated in rosacea." (PMID 39351216, 2024).
Splenomegaly (6 papers, 2017 to 2024). Abnormal increased size of the spleen. "OVX female mice that also received anti- IL-1α/β antibodies developed a high frequency of abscess development (7/10) and signs of infection dissemination including weight loss (P<0.04) and splenomegaly compared with controls (P<0.04)." (PMID 28358036, 2017). "Neutralization of IL-1α, and to a much lesser extent IL-1β, was associated with a significant increase in the mortality of R. typhi-, R. rickettsii-, and R. montanensis-infected mice and resulted in the development of splenomegaly, which correlated with an increase in bacterial loads in the spleen." (PMID 35130729, 2022). "All mice injected with 4T1/WT cells developed profound splenomegaly, while in mice injected with 4T1 IL-1α KO cells the changes in spleen size were mild." (PMID 38612760, 2024). "Indeed, the absence of RELMα led to increased circulating inflammatory cytokines including TNFα, IFNγ, IL-6 and IL-1α, and exacerbated splenomegaly." (PMID 34349768, 2021). "Alternatively, the corresponding occurrence of splenomegaly may induce down regulation of IL-1α signalling." (PMID 32877416, 2020). "In contrast only 1 of 8 female mice treated with the anti-IL-1α/β combination developed a small abscess, but did not exhibit weight loss or splenomegaly, indicating a localized lesion." (PMID 28358036, 2017). "Moreover, transfer of Il-1α−/− BMDMs resulted in the development of splenomegaly and an increase in bacterial burden in the spleens of Cl2MBP-treated WT mice, which correlated with a decrease in IL-1α serum concentrations without affecting IL-1β serum levels." (PMID 35130729, 2022).
trauma (6 papers, 2015 to 2023). "Proinflammatory cytokines, such as interleukin (IL)-1a and IL-1b, are implicated in the molecular cascade leading to neuronal injury after brain trauma." (PMID 32164605, 2020). "A patient-reported history of recent head trauma was present in 30/51 (61%) patients, and only IL-1α (p = 0.025) and TNF-α (p = 0.026) showed significantly higher inflammatory mediator concentrations in these patients." (PMID 36158966, 2022). "Chest trauma led to elevated expression levels of inflammatory and coagulatory proteins (such as TNFα receptor, IL-1α, IL-1β, C3, NF-κB and plasminogen activator)." (PMID 26303896, 2015). "Moreover, we demonstrated that dasatinib treatment effectively ameliorated inflammatory manifestations in SP-induced acute lung injury in mice, characterized by the increased levels of IL-1α, IL-1β, CXCL1, neutrophils, and M1 macrophages." (PMID 37705538, 2023).